PDPN (podoplanin)
Diseases named in the same sentence as PDPN in open-access papers (continued):
Sharing a sentence is not in itself a finding about the gene and the disease.
Coronary Artery Disease (2 papers, 2025 to 2026). "Low serum podoplanin concentrations are associated with an increased risk of coronary artery disease." (PMID 41465476, 2025). "This prospective study suggests that lower levels of serum podoplanin (PDPN) concentrations are associated with an increased risk of coronary artery disease (CAD) and may serve as a novel biomarker." (PMID 41465476, 2025). "Our results suggest a novel, independent mechanism from antiplatelet action, highlighting a possible role of platelets and their receptors in the functions of PDPN in coronary artery disease." (PMID 41465476, 2025). "Low-serum PDPN concentrations characterize patients with coronary artery disease." (PMID 41594182, 2026). "Low serum podoplanin concentrations characterized patients with coronary artery disease." (PMID 41465476, 2025). "This study aimed to compare possible differences in the serum podoplanin concentration between patients with angiographically proven de novo coronary artery disease and a control group (patients with normal coronary angiograms) to assess its potential as a CAD biomarker." (PMID 41465476, 2025).
coronary atherosclerosis (2 papers, 2025 to 2026). Atherosclerosis of the coronary vasculature. "In our analysis, we observed decreased PDPN serum concentrations, potentially due to chronic ischemia that causes a loss of podoplanin-expressing myocardial and endothelial cells secondary to coronary atherosclerosis." (PMID 41465476, 2025). "Our analysis investigated serum PDPN levels in coronary atherosclerosis, in contrast to previous histopathologic reports that revealed PDPN in aortic plaques." (PMID 41465476, 2025). "PDPN can be considered a novel marker for coronary atherosclerosis." (PMID 41594182, 2026). "Additionally, podoplanin’s involvement in vascular remodeling suggests a broader role in the progression of vascular diseases beyond coronary atherosclerosis." (PMID 41465476, 2025). "Podoplanin (PDPN) can be considered a novel marker for coronary atherosclerosis." (PMID 41465476, 2025). "On the other hand, our results, focused on the chronic state, suggest a possible link between lower podoplanin levels and coronary atherosclerosis, which may be explained by several possible mechanisms." (PMID 41465476, 2025).
COVID-19 (2 papers, 2022 to 2025). A disease caused by infection with severe acute respiratory syndrome coronavirus 2. "In our study, we characterized the presence of EVs derived from red blood cells (CD235a+), total leucocytes (CD45+), LEC (CD45− podoplanin+), blood endothelial cells (CD45− CD62e+) and platelets (CD45−, C-type lectin-like type II + (CLEC2+)) in the plasma of COVID-19 convalescent donors." (PMID 35337162, 2022).
diabetic nephropathy (2 papers, 2025 to 2026). "In our analysis of diabetic patients, lower podoplanin levels were associated with diabetic nephropathy." (PMID 41465476, 2025). "Recent evidence has shown that serum PDPN levels are elevated in diabetic nephropathy and correlate with disease progression, suggesting an association between PDPN and chronic metabolic–inflammatory states." (PMID 41594182, 2026).
emphysema (2 papers, 2022). "Using immunohistochemical analysis for PDPN, we found no change in the density of lung lymphatics in patients with emphysema compared to control smokers, in agreement with our microarray data." (PMID 35322079, 2022).
endometriosis (2 papers, 2017 to 2020). The growth of functional endometrial tissue in anatomic sites outside the uterine body. "While ALDH1A1 mRNA expression is significantly reduced in endometriosis ME-SFCs, PDPN surface expression is significantly enhanced in endometriosis ME-SFCs." (PMID 36304708, 2020). "ME-SFCs cultured from endometriosis patients exhibit increased expression of PDPN on their surface when compared to ME-SFCs from controls (P < 0.01)." (PMID 36304708, 2020). "Because we observed increased PDPN expression on the surface of ME-SFCs from endometriosis patients vs. controls, we compared the migration of endometriosis ME-SFCs to control ME-SFCs using the standard scratch-migration assay." (PMID 36304708, 2020). "In addition, a significant reduction in ALDH1A1 gene expression and increased podoplanin surface expression were also observed in endometriosis ME-SFCs when compared to control ME-SFCs." (PMID 36304708, 2020). "We show that exposure of ME-SFCs from control subjects to TNF replicates the phenotypes we observed in ME-SFCs from endometriosis patients, including reduced decidualization, reduced expression of ALDH1A1, increased expression of PDPN, and enhanced migration capacity." (PMID 36304708, 2020).
endotoxemia (2 papers, 2017). "In particular, as the only cell population with significantly lower podoplanin expression solely in Pdpnfl/flVAV1cre+ mice following LPS, loss of podoplanin from BAL CD11b+CD11c+F4/80+ alveolar inflammatory macrophages may play a key role in limiting endotoxemia-induced inflammation in the lung." (PMID 28839100, 2017). "As disruption of CLEC-2-podoplanin axis during endotoxemia partially mimics the phenotype observed in CLEC2fl/flPF4cre+ mice, we assessed the role of anti-podoplanin antibody on the inflammatory reaction and immune cell recruitment during bacterial peritonitis." (PMID 29269852, 2017).
epithelioid hemangioendothelioma (2 papers, 2013). A low-grade malignant blood vessel neoplasm. "Podoplanin, a small mucin-like transmembrane protein that is immunoreactive to D2-40 antibody, is a promising new marker in identifying epithelioid hemangioendothelioma." (PMID 23533870, 2013).
epithelioid sarcoma (2 papers, 2013 to 2020). An aggressive malignant neoplasm of uncertain differentiation, characterized by the presence of epithelioid cells forming nodular patterns. "Podoplanin expression has only been rarely reported in epithelioid sarcoma, and it must be taken in consideration because its expression along with EMA characterizes neoplasms that derive from the skin adnexa." (PMID 23691400, 2013).
experimental autoimmune encephalomyelitis (2 papers, 2014 to 2017). An autoimmune demyelinating disease of the central nervous system that is produced experimentally in animals by the injection of homogenized brain or spinal cord in Freund's adjuvant. "In an experimental autoimmune encephalomyelitis murine model, Th17 cells also directly elicit formation of ectopic lymphoid follicle formation, by surface molecule podoplanin and secretion of IL-17." (PMID 28577559, 2017).
glottic carcinomas (2 papers, 2010 to 2012). "Higher levels of podoplanin expression were observed in glottic carcinomas (P = 0.01)." (PMID 20196862, 2010).
Granuloma (2 papers, 2017 to 2018). A compact, organized collection of mature mononuclear phagocytes, which may be but is not necessarily accompanied by accessory features such as necrosis. "Of interest, granuloma nodules in the heart showed similar accumulation of podoplanin and PDGFRβ co-presenting cells." (PMID 28333941, 2017). "We found a high density of podoplanin labeling in the granuloma nodules in the heart (1 month/granuloma), but not in the RA of the same samples (1 month/granuloma)." (PMID 28333941, 2017). "In the infarcted myocardium with no granulomas, the high occurrence of PDGFRβ in podoplanin-bearing cells was apparent as well, albeit at the later stages of wound repair, concomitantly with the scar development." (PMID 28333941, 2017).
HIV-1 infection (2 papers, 2010 to 2014). The type species of lentivirus and the etiologic agent of acquired immunodeficiency syndrome (AIDS). "Podoplanin therefore joins the list of host factors which can be incorporated into the HIV-1 envelope and impact HIV-1 infection by interacting with their cognate ligands." (PMID 20482880, 2010). "Our expression studies indicated that podoplanin is not expressed on stimulated, viable PBMCs and T-cell lines, and that podoplanin expression is not induced in C8166 T-cells and PBMCs by HIV-1 infection." (PMID 20482880, 2010).
hypercoagulability (2 papers, 2024 to 2025). "Particularly, the role of TF and podoplanin has been increasingly linked to hypercoagulability and development of VTE over the last years." (PMID 39168144, 2025).
infarction (2 papers, 2017 to 2019). A localised pathological necrosis of tissue resulting from obstruction of the blood supply usually by a thrombus, an embolus, or vascular torsion. "Unexpectedly, at 2 days after MI, there was a more than a 6-fold rise in the podoplanin immunoreactivity in the infarct BZ relative to earlier time points after MI (< 1 day) or myocardial area remote to infarction (RA) (2 days)." (PMID 28333941, 2017).
Keratocystic odontogenic tumor (2 papers, 2014 to 2024). An intraosseous odontogenic neoplasm that usually arises from the mandible. "Previous studies conducted in our laboratory investigated the association of podoplanin with cellular proliferative activity, determined by Ki-67 antibody, in ameloblastomas and keratocystic odontogenic tumors." (PMID 25480364, 2014). "The membranous and cytoplasmic expression of podoplanin was intensively concentrated at the basal layer of the epithelium in all keratocystic odontogenic tumors." (PMID 25480364, 2014). "So, in order to verify if podoplanin and ezrin are co-localized in keratocystic odontogenic tumors, we designed the present study." (PMID 25480364, 2014). "The aims of this study were to investigate the immunolocalization of ezrin and its relationship with the podoplanin expression in keratocystic odontogenic tumors." (PMID 25480364, 2014). "The immunohistochemical expressions of ezrin and podoplanin by odontogenic epithelium were evaluated in keratocystic odontogenic tumors using monoclonal antibodies." (PMID 25480364, 2014). "We have demonstrated the correlation between the podoplanin expression and the cellular proliferation index in keratocystic odontogenic tumors." (PMID 25480364, 2014). "Our results showed strong cytoplasmic ezrin and membranous podoplanin expressions in basal epithelial layer of all keratocystic odontogenic tumors." (PMID 25480364, 2014). "The Spearman test did not demonstrate statistically significant correlation between membranous or cytoplasmic podoplanin and ezrin expressions in keratocystic odontogenic tumors." (PMID 25480364, 2014). "The currently study was designed to analyze the immunolocalization of ezrin and its relationship with podoplanin expression in keratocystic odontogenic tumors." (PMID 25480364, 2014). "Moreover, both podoplanin and Ki-67 expressions were stronger and co-localized in keratocystic odontogenic tumors when compared to the orthokeratinized odontogenic cysts, an indolent lesion." (PMID 25480364, 2014). "The distribution of ezrin in odontogenic keratocystic tumors was more heterogeneous than that of podoplanin and statistically significant differences were observed among the localization of membranous ezrin and cytoplasmic or membranous podoplanin." (PMID 25480364, 2014). "Thus, our investigation suggests a role for ezrin and podoplanin in keratocystic odontogenic tumors and their molecular interactions need to be further explored in these kinds of tumors." (PMID 25480364, 2014). "The podoplanin activated form (membranous) was mostly found in the basal layer, indicating a co-localization of active-ezrin and active-podoplanin in the highly active areas of keratocystic odontogenic tumors." (PMID 25480364, 2014).
kidney damage (2 papers, 2010 to 2021). "Podocytes, which are visceral epithelial cells of the kidney, express podoplanin and were found to be infected in HIV-1 patients and to proliferate in HIV-1 associated nephropathy." (PMID 20482880, 2010).
laryngeal carcinoma (2 papers, 2010 to 2012). Carcinoma that arises from the laryngeal epithelium. "Prospective studies involving larger numbers of patients are needed to further evaluate the clinical utility of podoplanin as a biomarker for laryngeal cancer risk assessment providing additional value beyond the clinical and histological markers." (PMID 20196862, 2010). "Podoplanin expression increases in the early stages of laryngeal tumourigenesis and it seems to be associated with a higher laryngeal cancer risk." (PMID 20196862, 2010). "The expression of podoplanin in the dysplastic lesions was correlated with the risk of progression to laryngeal cancer." (PMID 20196862, 2010). "We therefore investigated the expression pattern and clinical significance of podoplanin during the development and progression of laryngeal carcinomas." (PMID 20196862, 2010). "In this study cohort, the histology of the lesions does not have a significant role in assessing laryngeal cancer risk, and podoplanin seems a stronger predictor." (PMID 20196862, 2010). "However, our study is the first to analyse podoplanin expression in both laryngeal premalignant lesions and laryngeal carcinomas and its relationship with clinico-pathological parameters and prognosis." (PMID 20196862, 2010). "Podoplanin expression in laryngeal carcinomas exhibited two distinct patterns." (PMID 20196862, 2010). "The podoplanin and GST-T1 expression patterns were analyzed to determine their correlation with clinicopathologic parameters of laryngeal cancer." (PMID 24551781, 2012). "Patients carrying podoplanin-positive lesions had a higher laryngeal cancer incidence than those with negative expression reaching borderline statistical significance (51% versus 30%, P = 0.071)." (PMID 20196862, 2010). "At 5 years after the patients were diagnosed, 30% of the patients with negative podoplanin expression developed laryngeal cancer compared with 51% of the patients with positive podoplanin expression (P = 0.071)." (PMID 20196862, 2010). "Taken together, these data support a role for podoplanin expression in the initiation but not in the progression of laryngeal cancers." (PMID 20196862, 2010). "Taken together, these data support a role for podoplanin expression in the initiation rather than in the progression of laryngeal cancers." (PMID 20196862, 2010). "Therefore, it was proposed that the podoplanin expression may play a role in the initiation, but not in the progression of laryngeal cancers." (PMID 24551781, 2012).
laryngeal squamous cell carcinoma (2 papers, 2010 to 2012). A squamous cell carcinoma that arises from the larynx. "Clinico-pathological characteristics of the laryngeal squamous cell carcinomas and correlations with podoplanin expression." (PMID 20196862, 2010). "We have demonstrated for the first time that podoplanin is expressed in a high percentage of laryngeal dysplasias and laryngeal squamous cell carcinomas." (PMID 20196862, 2010). "In this study we found that podoplanin is expressed in a high percentage of dysplastic lesions and squamous cell carcinomas of the larynx." (PMID 20196862, 2010). "Podoplanin expression in laryngeal squamous cell carcinomas, however, diminishes during tumour progression." (PMID 20196862, 2010). "Podoplanin expression was determined by immunohistochemistry in paraffin-embedded tissue specimens from 84 patients with laryngeal premalignancies and 53 patients with laryngeal squamous cell carcinomas." (PMID 20196862, 2010). "The aim of this study is to determine whether there is a role of podoplanin and glutathione S-transferases T1 (GST-T1) expression in laryngeal squamous cell carcinoma." (PMID 24551781, 2012). "Podoplanin expression in laryngeal squamous cell carcinomas, however, diminishes during tumour progression and does not correlate with invasive potential." (PMID 20196862, 2010).
liver disease (2 papers, 2023 to 2025). "In addition, state #5 was identified as PDPN, FOXC2, and PROX2-expressing lymphatic-specific ECs; state #6 as a subpopulation expressing PLAT, whose protein level is increased in patients with liver disease; and, states #23, #32 and #34 as liver-specific liver sinusoidal ECs (LSECs)." (PMID 39748128, 2025).
medulloblastoma (2 papers, 2014 to 2017). A malignant, invasive embryonal neoplasm arising from the cerebellum. "In one study, podoplanin expression was observed in 83% and 27% of GBM and medulloblastoma cases, respectively." (PMID 28752098, 2017).
nephrosis (2 papers, 2023). Pathological processes of the KIDNEY without inflammatory or neoplastic components. "In puromycin aminonucleoside nephrosis, a rat model of human minimal change nephropathy, the extensive flattening of podocyte foot processes and severe proteinuria are observed in association with the high reduction of podoplanin expression." (PMID 37829206, 2023). "In experimental models of nephrosis, such as puromycin aminonucleoside-induced nephrosis and in Dahl SS rats, this striking alteration is preceded by PDPN down-regulation." (PMID 37298679, 2023).
oral lichen planus (2 papers, 2015 to 2025). Oral lichen planus is a chronic inflammatory oral condition of unknown aetiology characterized by T-cell-mediated chronic immune response and abnormal epithelial keratinization cycle. "The predictive value of podoplanin upregulation in other potentially malignant oral disorders, such as erythroplakia or oral lichen planus, also appears to be a promising tool, but further research is required." (PMID 41228241, 2025). "This reflection forces us to recommend the development of future primary-level studies to confirm, with larger sample sizes, whether podoplanin constitutes a valuable predictive tool for malignant transformation in oral lichen planus patients." (PMID 41228241, 2025).
pancreatic ductal adenocarcinoma (2 papers, 2021 to 2025). An infiltrating adenocarcinoma that arises from the epithelial cells of the pancreas. "A pan-cancer CAF marker remains elusive and podoplanin (PDPN) in pancreatic ductal adenocarcinoma (PDAC) may be the only consistent, disease-specific CAF marker identified in cancer to-date." (PMID 40379112, 2025).
pilocytic astrocytoma (2 papers, 2007 to 2022). Pilocytic astrocytoma is a rare subtype of low-grade glioma of the central nervous system characterized by a well circumscribed, often cystic, brain tumor with a discrete mural nodule and long, hair-like projections that extend from the neoplastic astrocytes. "First, leveraging human bulk RNA sequencing data, we identified PDPN as a gene differentially expressed both in NF1-associated and sporadic pilocytic astrocytomas relative to control non-neoplastic brain tissue." (PMID 35986378, 2022).
pregnancy diseases (2 papers, 2018 to 2020). "Podoplanin plays a role in foetal angiogenesis during placental development, and abnormal activity leads to pregnancy diseases associated with defective angiogenesis." (PMID 32260158, 2020).
Primary Sjogren’s Syndrome (2 papers, 2022 to 2025). "Deletion of the PDPN+ immunofibroblasts prevented the formation of tertiary lymphoid structures and reduced local immune pathology in Sjögren’s syndrome." (PMID 40084998, 2025).
rectal cancer (2 papers, 2011 to 2021). A primary or metastatic malignant neoplasm that affects the rectum. "We used D2-40 antibody (Podoplanin, cell surface sialylated glycoprotein) to stain lymphatic vessels in primary adenocarcinomas and mesorectal lymph nodes of 203 rectal cancer patients." (PMID 22087309, 2011).
Sézary syndrome (2 papers, 2015 to 2022). "There is a positive correlation between the number of podoplanin-positive vessels and disease progression in Sézary syndrome, which is considered the most severe cutaneous lymphoma." (PMID 35163233, 2022). "Therefore, podoplanin could be used as a predictive marker for the aggressive behavior in mycosis fungoides and Sézary syndrome." (PMID 35163233, 2022). "Furthermore, skin biopsy tissue from patients diagnosed with Sézary syndrome, a subtype of CTCL, also revealed an increase in lymph-angiogenesis as measured by an increased staining for podoplanin (PDPN), lymphatic vessel hyaluronan receptor-1 (LYVE-1), VEGF-C, and VEGF-R3." (PMID 25915535, 2015).